ITGA5 (integrin subunit alpha 5)
Description:
Integrin alpha-5/beta-1 (ITGA5:ITGB1) is a receptor for fibronectin and fibrinogen. It recognizes the sequence R-G-D in its ligands. ITGA5:ITGB1 binds to PLA2G2A via a site (site 2) which is distinct from the classical ligand-binding site (site 1) and this induces integrin conformational changes and enhanced ligand binding to site 1. ITGA5:ITGB1 acts as a receptor for fibrillin-1 (FBN1) and mediates R-G-D-dependent cell adhesion to FBN1. ITGA5:ITGB1 acts as a receptor for fibronectin (FN1) and mediates R-G-D-dependent cell adhesion to FN1. ITGA5:ITGB1 is a receptor for IL1B and binding is essential for IL1B signaling. ITGA5:ITGB3 is a receptor for soluble CD40LG and is required for CD40/CD40LG signaling. (Microbial infection) Integrin ITGA5:ITGB1 acts as a receptor for Human metapneumovirus. (Microbial infection) Integrin ITGA2:ITGB1 acts as a receptor for Human parvovirus B19. (Microbial infection) In case of HIV-1 infection, the interaction with extracellular viral Tat protein seems to enhance angiogenesis in Kaposi's sarcoma lesions.
Synonyms: CD49e; FNRA; VLA-5; VLA5A
Tractability: Small molecule: a high-quality ligand is known; it belongs to a druggable protein family. Antibody: a drug acting on it is in phase 2 or 3 trials; UniProt places it where antibodies can reach, with high confidence; its Gene Ontology location is reachable by antibodies, with high confidence; UniProt predicts a signal peptide or a membrane-spanning region. PROTAC: ubiquitination databases record sites on it; its protein half-life has been measured; a small molecule that binds it is known. Other modalities: a drug acting on it is in phase 2 or 3 trials.
Target class: Membrane receptor
Gene: Protein-coding gene on chromosome 12 (54,395,261 to 54,419,266, reverse strand). Ensembl gene ENSG00000161638.
Subcellular location: Cell membrane; Cell junction, focal adhesion
Pathways (Reactome):
Extracellular matrix organization: Elastic fibre formation; Fibronectin matrix formation; Integrin cell surface interactions
Cellular responses to stimuli: Mechanical load activates signaling by PIEZO1 and integrins in osteocytes; Turbulent (oscillatory, disturbed) flow shear stress activates signaling by PIEZO1 and integrins in endothelial cells
Developmental Biology: Signal transduction by L1
Gene expression (Transcription): RUNX2 regulates genes involved in cell migration
Hemostasis: Cell surface interactions at the vascular wall
Signal Transduction: GPER1 signaling
Gene Ontology:
Molecular function: calcium ion binding; protein binding; platelet-derived growth factor receptor binding; signaling receptor activity; vascular endothelial growth factor receptor 2 binding; cell adhesion molecule binding; epidermal growth factor receptor binding; integrin binding; signaling receptor binding
Biological process: CD40 signaling pathway; cell adhesion; cell adhesion mediated by integrin; cell-substrate adhesion; endodermal cell differentiation; heterotypic cell-cell adhesion; integrin-mediated signaling pathway; negative regulation of anoikis; positive regulation of sprouting angiogenesis; positive regulation of vascular endothelial growth factor signaling pathway; wound healing, spreading of epidermal cells; angiogenesis; cell-cell adhesion; cell-matrix adhesion; positive regulation of vascular endothelial growth factor receptor signaling pathway; female pregnancy; formation of primary germ layer; positive regulation of cell migration; positive regulation of cell-substrate adhesion; regulation of angiogenesis; response to muscle activity; tissue development
Cellular component: cell surface; cell-cell junction; focal adhesion; integrin alpha5-beta1 complex; plasma membrane; ruffle membrane; alphav-beta3 integrin-vitronectin complex; integrin complex; ruffle; cell junction; cytoplasmic vesicle; endoplasmic reticulum; external side of plasma membrane; glutamatergic synapse; Golgi apparatus; postsynaptic membrane; synapse
Genetic constraint (gnomAD): Loss-of-function variants: 53 observed, 146.7 expected, observed/expected ratio (o/e) 0.36, 90% interval 0.29 to 0.45. The upper end of that interval is the gene's LOEUF score, 0.45, which puts it in group 2 of 6, group 1 being the genes least tolerant of losing a copy. Missense variants: 1,130 observed, 1,356.6 expected, observed/expected ratio (o/e) 0.83, 90% interval 0.79 to 0.88. Synonymous variants: 500 observed, 545.08 expected, observed/expected ratio (o/e) 0.92, 90% interval 0.85 to 0.99.
Homologues: Orthologues: chimpanzee ITGA5 (99% identical), macaque ITGA5 (99% identical), pig ITGA5 (93% identical), rabbit ITGA5 (92% identical), dog ITGA5 (91% identical), mouse Itga5 (91% identical), guinea pig ITGA5 (90% identical), rat Itga5 (88% identical), tropical clawed frog itga5 (65% identical), zebrafish itga5 (55% identical), Caenorhabditis elegans pat-2 (27% identical), Drosophila melanogaster if (27% identical), and 3 more. Paralogues in human: ITGAV (46% identical), ITGA8 (45% identical), ITGA2B (36% identical), ITGA7 (27% identical), ITGA6 (27% identical), ITGA3 (24% identical), ITGA4 (24% identical), ITGA9 (23% identical), ITGAD (22% identical), ITGAX (22% identical), ITGA10 (22% identical), ITGAM (22% identical), and 5 more.
Diseases named in the same sentence as ITGA5 in open-access papers:
ITGA5 is named in the same sentence as 139 diseases in open-access papers, as found by Europe PMC text mining. Sharing a sentence is not in itself a finding about the gene and the disease. The quoted sentences say what the papers report.
breast cancer (56 papers, 2011 to 2026). A primary or metastatic malignant neoplasm involving the breast. "ITGA5 was associated with tumorigenesis, migration and invasion in breast cancer 41, liver cancer 42, colorectal cancer 43 and ovarian cancer cells." (PMID 33526991, 2021). "Using genetic silencing and overexpression strategies or pharmacological inhibition, we uncovered a specific association between ITGA5 expression levels in breast cancer and the development of bone metastasis." (PMID 33420367, 2021). "Of note, NDRG4 expression emerged in this study within a group of epigenetically silenced genes in breast cancer cells that were significantly associated with integrin pathways (e.g., ITGA5 and COL9A3)." (PMID 30963110, 2019). "Indeed, ITGA5 has been associated with lung metastasis in animal models of breast cancer." (PMID 33420367, 2021). "ITGA5 expression in invasive MDA-MB-468 cells was almost lost compared to other breast cancer cells." (PMID 38963646, 2025). "In triple-negative breast cancer cells with high ITGA5 expression, knockdown of ITGA5 or treatment with miR-30 mimics significantly reduces bone-metastatic burden in vivo, underscoring the pivotal role of ITGA5 in breast cancer bone dissemination." (PMID 40894924, 2025). "Further research should examine the involvement of CST7 in the infiltration of immune cells in breast cancer tissues and analyze possible connections between CST7, IL1B, and ITGA5 in relation to breast cancer." (PMID 39552709, 2024). "SRC‐1 enhances ITGA5 promoter activity via an AP‐1 binding site in breast cancer cells to promote breast cancer metastasis." (PMID 38506084, 2024). "MiR-31 has been shown to target key genes of cell migration such as RHOA and ITGA5 and attenuated breast cancer cell invasion." (PMID 37833432, 2023). "Multiple studies have shown that increased ITGA5 expression predicts poor prognosis of tumors, such as ovarian cancer, breast cancer, and lung cancer." (PMID 37007965, 2023). "cAMP response element-binding protein (CREB) transcription factor is a positive regulator of YAP1 transcription and an integrin alpha 5 (ITGA5)/FAK/CREB signaling axis was described to enhance YAP1 transcription in breast cancer." (PMID 36936987, 2023). "ITGA5 expression is an important factor that affects the prognosis of non-small cell lung and breast cancers with bone metastases." (PMID 37015905, 2023). "Experiments were also conducted with human MCF-7 breast cancer cells that express low amounts of ITGA5." (PMID 33420367, 2021). "ITGA5 mRNA expression levels in tumor cells were further investigated using 51 distinct breast cancer cell lines with different molecular phenotypes and degree of invasiveness (GSE12777)." (PMID 33420367, 2021). "It has previously been reported that ITGA5 promotes survival of breast cancer cells in the bone marrow." (PMID 33420367, 2021). "For instance, blocking the interaction between integrin α 5 (ITGA5) and Src-1 antagonized Src-1-induced metastasis of breast cancer." (PMID 34307888, 2021). "It was reported that the expression of ITGA5 is also increased in many solid primary mammary tumors and it promotes tumor cell growth and survival." (PMID 32865767, 2021). "Cdh11 or Itga5 silencing in bone-tropic breast cancer cells recapitulates the inhibitory effect of miR-30s on bone metastasis formation in animal models, further confirming that these effector oncogenes are regulated by miR-30s." (PMID 33830428, 2021). "In breast cancer, ITGA5 mediates tumor cell adhesion, extracellular matrix-guided directional migration along fibronectin, and tumor cell survival in vitro." (PMID 33420367, 2021). "Using genetic overexpression or silencing strategies, we show that ITGA5 in breast cancer cells mediates metastatic tumor cell colonization of the bone marrow and promotes formation of osteolytic lesions in vivo." (PMID 33420367, 2021).
breast cancer (continued). "High ITGA5 expression in primary tumors correlated with the presence of disseminated tumor cells in bone marrow aspirates from early stage breast cancer patients (n = 268; p = 0.039)." (PMID 33420367, 2021). "Overall, these data indicated that ITGA5 mediates the homing of breast cancer cells in the bone marrow and promotes formation of osteolytic bone metastases in vivo." (PMID 33420367, 2021). "Of note, miR-205 (like miR-30s) also targets the integrin ITGA5, which plays an essential role in mediating breast cancer bone metastasis formation." (PMID 33830428, 2021). "Conversely, members of the miR-30 family impede breast cancer bone metastasis formation by directly targeting ITGA5." (PMID 33420367, 2021). "It has been reported that miR-31 possessed multiple mechanisms to inhibit breast cancer metastasis by partial coordination to repress the metastasis-promoting genes, such as RhoA, ITGA5 and RDX." (PMID 27174918, 2016). "Although NCOA1 is known to promote breast cancer metastasis through working with multiple transcription factors to upregulate the expression of Twist1, ITGA5, CSF-1, SDF1 and CXCR4, the role of NCOA1 in breast tumor angiogenesis has not been investigated." (PMID 26287601, 2015). "miR-31, a well-known anti-metastatic miRNA in breast cancer, was first shown to inhibit breast cancer metastasis both in vitro and in vivo through the targeting of integrin-α5 (ITGA5), radixin (RDX) and RhoA and later through targeting of WAVE3." (PMID 25927669, 2014). "ITGA5 is down-regulated in transformed plasma cells compared to normal plasma cells and in highly invasive potential breast cancer cell lines." (PMID 22724020, 2012). "Our data shows that alcohol exposure increases the expression of the fibronectin receptor subunit ITGA5 in T47D breast cancer cells." (PMID 21838876, 2011). "While Nm23 works to prevent the spread of breast cancer, ITGA5 produces an integral membrane protein that increases the metastasis of breast cancer cells." (PMID 21838876, 2011). "Results show that down-regulating ITGA5 significantly inhibited the ability of T47D breast cancer cells to invade (p < 0.05)." (PMID 21838876, 2011). "Nevertheless, our results indicate that alcohol decreases the expression of Nm23, thereby allowing ITGA5 to be expressed, which in turn allows T47D breast cancer cells to obtain a more invasive phenotype." (PMID 21838876, 2011). "To determine the relationship between Nm23 and ITGA5 in alcohol-treated T47D breast cancer cells, we knocked down each gene separately and in combination, using small interfering RNA (siRNA), and subsequently measured cell invasion." (PMID 21838876, 2011). "In the present study, we identify and examine the roles of two genes, Nm23 and ITGA5, in alcohol-induced breast cancer cell invasion." (PMID 21838876, 2011). "Alcohol exposure in human breast cancer T47D cells down-regulated expression of the Nm23 metastasis suppressor gene, leading to increased expression of the ITGA5 fibronectin receptor subunit, and consequently induced cellular invasion in vitro." (PMID 21838876, 2011). "Integrin α5 (ITGA5) expression increased in BA-treated breast and breast cancer stem cells." (PMID 38963646, 2025). "ITGA5 could promote the adhesion of cancer cells to the bone in breast cancer, which is related to bone metastasis of breast cancer." (PMID 36742137, 2023). "Targeting ITGA5 to inhibit breast cancer cell migration has been recently achieved through different approaches with decreased metastasis capacity, thus demonstrating the potential of this approach for breast cancer therapy." (PMID 37904233, 2023). "miR-148b has also been found to target ITGA5 to mediate the tumorigenesis of breast cancer." (PMID 36765401, 2023). "Moreover, Park & al. demonstrated in MCF10 breast cancer cells overexpressing SRSF6 that ITGA5, ITGB2 and ITGB6 were overexpressed and alternative splicing variants of ITGB2, ITGB4, SRSF6 and ATXN2 were detected." (PMID 37904233, 2023).
breast cancer (continued). "Our study establishes a bone metastasis-promoting role for ITGA5 in breast cancer." (PMID 33420367, 2021). "Here, we showed that ITGA5 silencing reduced the survival of breast cancer cells." (PMID 33420367, 2021). "We therefore focused our attention to the role of ITGA5 in breast cancer bone metastasis." (PMID 33420367, 2021). "ITGA5 also mediates lung metastasis in animal models of breast cancer." (PMID 33420367, 2021). "In breast cancer cells, depletion of miR-214 can inhibit the vascular endothelial pathway of malignant cells by reducing the expression of the cell adhesion molecules ITGA5 and ALCAM." (PMID 34818353, 2021). "Overall, this study identifies ITGA5 as a mediator of breast-to-bone metastasis and raises the possibility that volociximab/M200 could be repurposed for the treatment of ITGA5-positive breast cancer patients with bone metastases." (PMID 33420367, 2021). "Having shown that there is an explicit role for ITGA5 in mediating early breast cancer cell colonization in the bone marrow, we then investigated whether ITGA5 also plays a role in the development of metastatic skeletal lesions." (PMID 33420367, 2021). "Another study indicates, on the contrary, that ITGA5 might be essential for breast cancer metastatic capacity." (PMID 22724020, 2012). "Hence, it is tempting to speculate that this pathway may also promote breast cancer metastasis to the lung through its impact on ITGA5 expression." (PMID 37563605, 2023). "High expression of ITGA5 was also associated with poor prognosis in lung cancer (OS HR = 1.6, 95% CI = 1.4 to 1.81, P = 5.9e-13; DFS HR = 1.75, 95% CI = 1.44 to 2.12, P = 1.2e-08) and breast cancer (OS HR = 1.21, 95% CI = 0.96 to 1.52, P = 0.11; DFS HR = 1.28, 95% CI = 1.14 to 1.44, P = 4.1e-05)." (PMID 33711961, 2021). "NCOA1 has previously been reported to be overexpressed in breast cancer and its increased expression positively correlated with disease recurrence and metastasis through working with multiple transcription factors to, in turn, upregulate the expression of Twist1, ITGA5, CSF-1, SDF1 and CXCR4." (PMID 28060733, 2017). "Thus, down-regulation of Nm23 by alcohol may promote RhoA activation through estrogen regulation to favor ITGA5-mediated breast cancer progression." (PMID 21838876, 2011). "According to alcohol metabolism-involved genes, three were up-regulated (ITGA5, CBS, and SOD2), and six were down-regulated (XDH, XRCC1, MTHFR, CYP1B1, XPC, and GSTP1) among women who died for breast cancer." (PMID 39125744, 2024). "Since we recently demonstrated that that ITGA5 knock-down reduced both collective and IGDQ-mediated breast cancer cell migration this can explain how indacaterol inhibited cell migration." (PMID 37904233, 2023). "A significantly higher percentage of breast cancer patients having elevated ITGA5 protein levels in primary tumors were DTC-positive (p = 0.039), compared to that observed for patients with low ITGA5 levels in primary tumors." (PMID 33420367, 2021). "An example can be seen in breast cancer bone invasion, whereby miR-301a-d regulates DKK-1, RUNX-2 and ITGA5 genes, which are involved in osteogenesis, leading to breast cancer osteomimicry." (PMID 34680611, 2021). "We then examined gene expression from 9 different breast cancer datasets and found correlation between HIF1A and LOX, ITGA5, and FN1 mRNAs, supporting the upstream regulatory role of HIF1A in their transcription." (PMID 32415208, 2020). "Three genes were up-regulated (i.e., ITGA5, CBS, and SOD2), while six were down-regulated (i. e, XDH, XRCC1, MTHFR, CYP1B1, XPC, and GSTP1) among individuals who died of breast cancer." (PMID 32078659, 2020). "MDA-MB-231 breast cancer cell lines express high levels of ITGA2 / ITGB1, ITGA3 / ITGB1, ITGA5 / ITGB1, ITGAV / ITGB3 integrins, compared to MCF-7, T47D, and ZR75-1 breast cancer cells." (PMID 25593998, 2014).
breast cancer (continued). "Silencing of CDH11 or ITGA5 in breast cancer patients with ER/PR negative breast cancer cells recapitulated inhibitory effects of miRNA30 on skeletal tumor burden." (PMID 39742357, 2024). "Additional factors expressed by human breast cancer cells, such as PTH-rP and angiopoietin-2, promote tumor cell adhesiveness to fibronectin and tumor cell motility and invasion through the specific upregulation of ITGA5." (PMID 33420367, 2021). "We therefore silenced ITGA5 in claudin-low MDA-MB-231 and MDA-B02 breast cancer cells, the latter being a bone metastatic cell subpopulation of the MDA-MB-231 cell line, which constitutively and specifically overexpresses αvβ3 integrin compared to the parental cell line." (PMID 33420367, 2021). "Besides the role played by ITGA5 in promoting breast cancer cell adhesion, invasion, and survival, EFEMP2, KIAA1199, and MFAP5 also enhance breast cancer motility and invasiveness." (PMID 33420367, 2021). "We, therefore, treated 4175-TGL and SKBR3 breast cancer, MA-2 melanoma or A549 lung cancer cells, with GL21.T, axl-148b or scr-148b molecules and evaluated ALCAM and ITGA5 protein expression levels compared to cells transfected with miR-148b precursors (pre-148b) or controls (pre-ctrl)." (PMID 32174798, 2020). "To confirm differential gene expression levels in the three breast cancer subtypes, Her2+, ER + and TNBC, we selected 6 genes (ITGA3, ITGA5, OXTR, WNT5B, BCAR1, FZD1) with significantly different levels of expression based on our microarray studies and validated their expression levels by qRT-PCR." (PMID 22954256, 2012). "DepMap portal plots using publicly available data derived from human breast cancer cell lines and Gepia2 plots using publicly available tumor samples from patients with breast cancer demonstrated that TNBC subtypes show high expression levels of PTK2 (FAK), EGFR, ITGA5, ITGB1, and STAT3." (PMID 38315147, 2024). "Additionally, using a clinical cohort of breast cancer patients without any clinical signs of metastasis, we showed that high ITGA5 expression levels in primary tumors correlated with the presence of DTCs in the bone marrow." (PMID 33420367, 2021). "It was reported that ITGA5 was downregulated in breast cancer effusion compared to primary tumors; thus, it was stated that there may be a negative correlation between ITGA5 expression and breast cancer cell metastasis." (PMID 38963646, 2025). "However, our study suggests that additional molecular mechanisms associated with lung metastasis formation may likely compensate for the lack of ITGA5 in human breast cancer cells, whereas ITGA5 is crucial for the homing of these cancer cells in the bone marrow." (PMID 33420367, 2021).